LYN (LYN proto-oncogene, Src family tyrosine kinase)
Diseases named in the same sentence as LYN in open-access papers (continued):
Sharing a sentence is not in itself a finding about the gene and the disease.
cervical cancer (6 papers, 2016 to 2024). A primary or metastatic malignant neoplasm involving the cervix. "Colony formation assays, wound healing, transwell invasion assay and flow cytometer analysis were performed to investigate the roles that miR-218-5p and LYN played in migration, invasion and death of cervical carcinoma." (PMID 30524205, 2018). "In our research, we found that the expression of LYN was significantly higher in cervical cancer tissues than that in cancer adjacent normal cervical tissues and normal cervical tissue." (PMID 27690342, 2016). "The expression of LYN significantly increased in cervical cancer tissues than that in cancer adjacent normal cervical tissues and normal cervical tissue (P <0.05)." (PMID 27690342, 2016). "Meanwhile, IL-6 is one of the key activators of STAT3, so we treated it to cervical cancer cell lines to reveal the relationship among IL-6R/LYN/STAT3." (PMID 27690342, 2016). "Immunohistochemistry identified that LYN expression was significantly increased in cervical cancer tissues than that in cancer adjacent normal cervical tissues and normal cervical tissues." (PMID 27690342, 2016). "IHC evaluation of LYN was performed on a commercial tissue microarray containing 192 cervical cancer tissues, 15 cancer adjacent normal cervical tissues and 1 normal cervical tissue." (PMID 27690342, 2016). "All these results indicated that LYN promoted cervical cancer cells metastasis through activating IL-6/STAT3 pathway." (PMID 27690342, 2016). "In order to investigate the function of LYN in cervical cancer, we employed lentiviral vector to study the functional assays of LYN knockdown and overexpression." (PMID 27690342, 2016). "Xenograft tumorigenesis in nude mice was used to explore the effect of LYN on tumor formation of cervical cancer." (PMID 27690342, 2016). "MiR-218-5p suppressed the progression of cervical cancer via LYN/NF-κB signaling pathway." (PMID 31157166, 2019). "The expression of miR-218-5p was low but LYN was high in cervical cancer (CC) primary tumors." (PMID 30524205, 2018). "In terms of mechanism, LYN could also promote cervical cancer cells metastasis through activating IL-6/STAT3 pathway." (PMID 27690342, 2016). "However, little is known about the relationship between LYN and cervical cancer, as well as the cellular function of LYN in cervical cancer." (PMID 27690342, 2016). "In order to determine whether IL-6 could regulate LYN expression in cervical cancer cell lines, we analyzed LYN expression in SiHa and C33a cells after IL-6 treatment." (PMID 27690342, 2016). "Nonetheless, little study has evaluated the role of LYN in cervical cancer." (PMID 27690342, 2016). "We found that LYN could bind to P-STAT3 in cervical cancer cells." (PMID 27690342, 2016). "LYN may play an important role in tumorigenesis of cervical cancer." (PMID 27690342, 2016). "The candidate genes SPP1, FOXM1, LYN, COL6A3, CCL21, TTK and MELK at mRNA level, emerge as promising candidate markers for cervical cancer prognosis and also emerge as potential therapeutic drug targets." (PMID 33829064, 2021). "Western blot analysis confirmed that LYZ, ORM1, LYN, STMN1 significantly increased in cervical cancer, while LUM, BGN, KRT4 significantly decreased." (PMID 27690342, 2016). "We found that LYZ, ORM1, LYN and STMN1 significantly increased in cervical cancer samples." (PMID 27690342, 2016).
melanoma (6 papers, 2019 to 2025). A malignant, usually aggressive tumor composed of atypical, neoplastic melanocytes. "Results of an in vitro study showed that LYN knockdown inhibited the proliferation, migration and invasiveness of melanoma cells." (PMID 35433689, 2022). "LYN is a tyrosine kinase which is deregulated in a variety of cancers like breast, prostate, melanoma, and cervix." (PMID 33829064, 2021). "YUSIV melanoma cell line, the most sensitive to inhibition by SAB298, required LYN for optimal cell proliferation, whereas there was only at most 50% reduction in growth in response to downregulation of YES and FYN." (PMID 31040916, 2019). "Notably, STAT1 was involved exclusively in Stage 4–specific synergistic relationships within the melanoma network, whereas TNFSF14, STK17B, SAMD3, PLAC8, and LYN were all Stage 1–specific synergistic genes that synergized with FENDRR." (PMID 40728857, 2025). "Interestingly, knockdown expression revealed that melanoma cells sensitive to the compound are “addicted” to SRC and LYN activity." (PMID 31040916, 2019).
renal carcinoma (6 papers, 2012 to 2025). A carcinoma arising from the epithelium of the renal parenchyma or the renal pelvis. "Src kinase signaling members were also predominant in the core, including SRC, LCK, LYN, FYN and PTPN6, among which LYN has been causally implicated in renal cancer." (PMID 29861861, 2018). "LYN, another Src family kinase member, is associated with poor prognosis in renal cancer patients." (PMID 40612864, 2025). "In other target gene of miR-205 in renal cancer cells, it was also demonstrated the similar binding pattern in targeting of LYN 3′-UTR by miR-205." (PMID 22859986, 2012).
chronic lymphocytic leukemia (5 papers, 2015 to 2025). "For instance, the dysregulation of NF-κB in chronic lymphocytic leukemia (CLL) cells causes overexpression of anti-apoptotic genes; CLL cells have elevated SYK, LYN, and BTK expression and elevated PI3K activity." (PMID 29907126, 2018). "In chronic lymphocytic leukemia, for instance, LYN has been demonstrated to be essential for the formation of a microenvironment supporting leukemic growth, and hence in such a situation, a high selectivity for LYN inhibition would be desirable." (PMID 39676406, 2025). "In chronic lymphocytic leukemia (CLL) cells, LYN overexpression led to PP2A-C hyperphosphorylation and inactivation via increased association of PP2A-C with the PP2A inhibitor, SET." (PMID 32759757, 2020). "LYN, a tyrosine kinase, is integral to internal signaling processes and is crucial for the differentiation and persistence of the leukemic phenotype across various blood cancers including AML, CML, and B-cell lymphocytic leukemia." (PMID 40608798, 2025). "In addition, LYN is important for maintaining the leukemic phenotype of various leukemic disorders including AML, CML, and B-cell lymphocytic leukemia." (PMID 26065685, 2015).
gastric cancer (5 papers, 2015 to 2021). A primary or metastatic malignant neoplasm involving the stomach. "QPCR result showed that miR-496 mimics significantly inhibited the expression of LYN in the AGS cells suggesting that LYN was a downstream target of miR-496 in gastric cancer." (PMID 34514167, 2021). "In conclusion, miR-496 inhibited the proliferation through the AKT/mTOR signaling pathway via targeting LYN in gastric cancer cells." (PMID 34514167, 2021). "Expression of SRC, LYN and CKB in gastric cancer is significantly associated with tumor invasion and lymph node and distant metastases, as well as with MYC expression, which is also a possible biomarker for GC." (PMID 26460485, 2015). "We found that reduced SRC and LYN methylation and increased CKB methylation was associated with gastric cancer." (PMID 26460485, 2015). "Finally, we explored the molecular mechanism by which miR-496/LYN regulated the growth of gastric cancer." (PMID 34514167, 2021). "Therefore, we hypothesize that miR-496/LYN/AKT/P70 may be a cell growth regulatory pathway in gastric cancer cells." (PMID 34514167, 2021). "In order to elucidate whether miR-496 exerts tumor suppressive effect in gastric cancer through LYN, we transfected miR-496 mimics and LYN overexpression plasmid (miR-496 & LYN) in AGS cell line at the same time, and detected the cell proliferation and apoptosis with miR-496 mimics as a control." (PMID 34514167, 2021). "However, the role of miR-496 and LYN in gastric cancer still remains unclear and needs further exploration." (PMID 34514167, 2021). "In conclusion, miR-496 inhibits the proliferation and metastasis and induces the apoptosis through targeting LYN and inhibiting the AKT/mTOR signaling pathway in gastric cancer." (PMID 34514167, 2021). "Thus, we hypothesized that LYN was the downstream direct target of miR-496 in gastric cancer cells." (PMID 34514167, 2021). "We screened out five overlapping Shc1-binding proteins (JUP, EPHA2, RASAL2, LYN, and SHCBP1), which were positively correlated with HER2 expression and were upregulated in gastric cancer." (PMID 33990570, 2021). "In this study, we aimed to evaluate SRC, LYN and CKB protein and mRNA expression, as well as their promoter methylation, in gastric cancer." (PMID 26460485, 2015).
prostate carcinoma (5 papers, 2015 to 2023). A carcinoma that arises from epithelial cells of the prostate gland. "LYN promotes tumorigenesis; for example, it triggers the initiation of prostate cancer in a regenerated prostate murine model." (PMID 27756880, 2016).
psoriasis (5 papers, 2015 to 2021). An autoimmune condition characterized by red, well-delineated plaques with silvery scales that are usually on the extensor surfaces and scalp. "MiR-210 was reported to be increased and to regulate Th17 and Th1 cells by inhibiting the expression of STAT6 and LYN in psoriasis." (PMID 34140947, 2021). "Expression of this miRNA has also been found to be over-expressed in both psoriasis patients and psoriasis animal models where it stimulates Th17 and Th1 cell differentiation but suppresses Th2 differentiation via inhibiting expressions of STAT6 and LYN." (PMID 34804042, 2021).
Autoimmunity (4 papers, 2017 to 2022). The occurrence of an immune reaction against the organism's own cells or tissues. "Previous studies have indicated that dendritic cell-induced autoimmunity and inflammation resulted from LYN dysregulation." (PMID 36263434, 2022).
breast tumors (4 papers, 2007 to 2024). "Nevertheless, according to previous findings in the literature, many identified markers upregulated in our non-responder datasets (e.g., LYN) are relevant for a broad spectrum of breast tumors." (PMID 38256136, 2024). "Importantly, the downregulation of the tyrosine kinase Lck/Yes-Related Novel Protein (LYN) was reported to prevent breast tumor invasion and metastasis, and ICI treatment combined with anti-LYN therapy might improve the efficacy of ICIs." (PMID 37214475, 2023).
oral cancer (4 papers, 2014 to 2018).
ovarian carcinoma (4 papers, 2013 to 2020). A malignant neoplasm originating from the surface ovarian epithelium. "Conversely, high LYN expression was associated with good prognosis in ovarian cancer." (PMID 29937990, 2018). "PIN1 knockdown suppressed LYN Y397 phosphorylation in COV 362 cells (BRCA1 mutant ovarian carcinoma) and PEO-1 and PEO-4 cells (BRCA2 mutant ovarian carcinoma), but not in KURAMOCHI cells (BRCA2 mutant ovarian carcinoma)." (PMID 30590041, 2018).
pancreatic cancer (4 papers, 2017 to 2024). "Alternatively, another signaling node of LYN in pancreatic cancer involves the megakaryocyte-associated tyrosine kinase (MATK)." (PMID 33233470, 2020). "Mutations in the BRCA2 gene have been implicated in pancreatic cancer susceptibility, whereas the knockdown of LYN reduced human pancreatic cancer cell proliferation, migration, and invasion." (PMID 28347313, 2017). "LYN, as an important member of the SCR family, plays an important role in the disease progression of pancreatic cancer." (PMID 38739359, 2024).
Sepsis (4 papers, 2021 to 2025). Sepsis is defined as life-threatening organ dysfunction caused by a dysregulated host response to infection. "In the sepsis-associated acute kidney injury (SA-AKI) model, the deletion of the LYN gene exacerbates tubular injury." (PMID 40692778, 2025). "In the GSE64456 control and sepsis groups, LYN (tyrosine protein kinase Lyn), and IFI16 (interferon gamma-inducible protein 16) had degree 56 and 70, respectively." (PMID 33667236, 2021). "Additionally, THCQ has been found to regulate critical target genes in sepsis patients (such as MAPK14, MAPK3, MMP9, STAT3, and LYN), which play key roles in cellular inflammatory responses, especially through the modulation of the MAPK and Nrf2 pathways." (PMID 40963685, 2025). "The upregulation of FcγR‐related genes, such as FCGR3A, FCGR1A, LYN, SYK, FYN and SRC, was detected in the prefrontal cortex, hippocampus, heart and colon of our sepsis patients, but not in the kidneys or lungs." (PMID 37731199, 2023).
acute lymphoblastic leukemia (3 papers, 2020 to 2025). Leukemia with an acute onset, characterized by the presence of lymphoblasts in the bone marrow and the peripheral blood. "Kinase profiling revealed that GNF-7 not only evidently inhibited LYN, FYN, SRC, YES, BTK and CSK kinase that can also inhibited by dasatinib, but also inhibited ACK1 and mitogen-activated protein kinase (GCK) to kill NRAS-dependent cells in AML and acute lymphoblastic leukemia." (PMID 38037057, 2023). "Moreover, calpain inhibition (calpain inhibitor II or CPI-2) also induces apoptosis among acute lymphoid leukemia (ALL) and non-Hodgkin’s lymphoma B cells, which is dependent on caspase activation but not on the protein tyrosine kinases LYN or Bruton’s tyrosine kinase (BTK)." (PMID 41294867, 2025).
Alzheimer disease (3 papers, 2023 to 2025). A progressive, neurodegenerative disease characterized by loss of function and death of nerve cells in several areas of the brain leading to loss of cognitive function such as memory and language. "HSP90, HSPA5, and LYN are implicated in key Alzheimer’s disease pathologies, including neuroinflammation and disrupted protein homeostasis." (PMID 40732226, 2025). "Phosphorylated LYN has also been observed in post-mortem brain from Alzheimer’s patients, and genome-wide association studies identified LYN as an increased risk factor for the development of late-onset Alzheimer’s disease." (PMID 37910561, 2023). "Nilotinib’s strong positive connectivity with HSP90, HSPA5, and LYN suggests repurposing potential for Alzheimer’s disease." (PMID 40732226, 2025). "In the Alzheimer’s disease (AD) model, LYN directly binds to TLR4 and regulates the inflammatory and phagocytic functions of microglia." (PMID 40692778, 2025).
asthma (3 papers, 2012 to 2022). "In addition, LYN is a central effector of mucus hypersecretion and endoplasmic reticular stress in asthma and participates in the regulation of airway inflammation, airway remodeling, and airway hyperresponsiveness through multiple mechanisms, thereby exacerbating asthma." (PMID 35572723, 2022). "Therefore, suppression of LYN could be a possible target for asthma treatment by H. cuspidatus." (PMID 35572723, 2022).
B cell lymphoma (3 papers, 2006 to 2023). "The inhibition of LYN, notably with Dasatinib, is an important strategy for the treatment of B-ALL and B-cell lymphoma." (PMID 36765939, 2023). "LCK homologue protein LYN (Lck/Yes-related novel protein tyrosine kinase) is more specifically expressed by B-cell lymphoblastic leukemia (B-ALL) and B-cell lymphoma and is important for BCR signaling." (PMID 36765939, 2023). "Further, LYN expression levels in HMC-1 (mast cell), HEL (human erythroleukemia cells), U-698 (human B cell lymphoma), HDLM-2 (human Hodgkin lymphoma), and Karpas-707 (human myeloma) cell lineages were relatively high based on Cancer Cell Line Encyclopedia (CCLE)." (PMID 35186945, 2021).
periodontitis (3 papers, 2021 to 2024). An acute or chronic inflammatory process that affects the tissues that surround and support the teeth. "This means that FYN, LYN and LCK, which are highly expressed, play an important role in the imbalance of the immune system of periodontitis." (PMID 33841510, 2021).
colorectal tumor (2 papers, 2006 to 2015). "LYN upregulation was associated with colorectal tumor grade, stage, and lymph node and distant metastases." (PMID 26460485, 2015). "It has been reported before that LYN is expressed in colorectal tumors." (PMID 16982006, 2006).
dementia (2 papers, 2023 to 2024). Loss of intellectual abilities interfering with an individual's social and occupational functions. "Interestingly, in our study, KLK4 and LYN were identified as among the best discriminative plasma proteins for dementia in the MUVR model." (PMID 37175824, 2023). "Four protective proteins (PLEK, DAPP1, CSK and CASP3) that decreased postinfection in the BLSA were significantly decreased in dementia cases in the ARIC study, with several other protective proteins (EIF4A1, DSG1, PIK3CG, PRKCB and LYN) showing similar trends." (PMID 39143319, 2024).
Ewing sarcoma (2 papers, 2010 to 2015). A small round cell tumor that lacks morphologic, immunohistochemical, and electron microscopic evidence of neuroectodermal differentiation. "In some other studies, kinases such as JNK, TOPK, AURKA, AURKB and LYN have all been studied in Ewing's sarcoma." (PMID 20718987, 2010). "In addition, the inhibition of LYN was able to decrease primary tumor growth, reduce metastases in an in vivo model of Ewing’s sarcoma, and decrease the invasive capacity of Ewing’s sarcoma cells in vitro." (PMID 26460485, 2015). "The siRNA against LYN, TOPK and JNK did not affect Ewing's sarcoma cell proliferation while siRNA against AURKA had only a marginal effect." (PMID 20718987, 2010).
lung adenocarcinoma (2 papers, 2016 to 2020). A carcinoma that arises from the lung and is characterized by the presence of malignant glandular epithelial cells. "Because LYN expression is associated with clinical outcomes in lung adenocarcinoma, and in patients with ADC in general, we examined the functions of LYN in ADC cell lines." (PMID 27756880, 2016).
lymphoid tumors (2 papers, 2018 to 2022). "Constitutive activation of LYN and SYK has been shown to promote BTK-independent activation of the BCR cascade in ibrutinib-resistant lymphoid tumors." (PMID 35296646, 2022). "Additional therapeutic targets in lymphoid tumors addicted to chronic BCR activation include SYK, LYN, and PKCβ." (PMID 29587428, 2018).
lymphopenia (2 papers, 2018 to 2021). Reduction in the number of lymphocytes. "We also observed that lymphopenia was temporally associated with the upregulation of CCR2, LYN, PAK1, PTK2B, SRC, STAT3, which are involved in the chemokine signaling pathway." (PMID 30713538, 2018).
neuroblastoma (2 papers, 2015 to 2023). Neuroblastoma (NB) is the most common solid, extracranial childhood tumor. "This is consistent with previous work showing that FYN and LYN show different responses in activity, association with the scaffold protein PAG1, and intracellular localization when activated by different RTKs in neuroblastoma cells." (PMID 36996232, 2023).
non-small cell lung carcinoma (2 papers, 2016 to 2020). A group of at least three distinct histological types of lung cancer, including non-small cell squamous cell carcinoma, adenocarcinoma, and large cell carcinoma. "In conclusion, our research indicates that LYN, C3, COPG2ITL, HLA.DQAL, and TNFRSFL17 are potential prognostic markers for non-small cell lung cancer." (PMID 33215029, 2020). "LYN, C3, COPG2IT1, LA.DQA1, and NFRSF17 may be new immune markers to judge the prognosis of patients with non-small cell lung cancer." (PMID 33215029, 2020).
Obesity (2 papers, 2013 to 2021). Accumulation of substantial excess body fat. "Notably, FCER1G, LYN and SYK downregulation were able to reduce obesity induced by high-fat diet and the growth of lipid droplets in adipocytes." (PMID 34506234, 2021).